CXCL9 (C-X-C motif chemokine ligand 9)
Diseases named in the same sentence as CXCL9 in open-access papers (continued):
Sharing a sentence is not in itself a finding about the gene and the disease.
liver fibrosis (continued). "There is not much available information of the relationship between CXCL9-11 polymorphisms and liver fibrosis in CHC." (PMID 28755163, 2017). "Interestingly, DBMSCs also express CXCL9 which is known for its function against angiogenesis and liver fibrosis." (PMID 27087815, 2016). "A strong association between CXCR3-associated chemokines CXCL9 and CXCL10 with liver fibrosis suggested that they may have promise as new non-invasive markers of liver fibrosis in HCV infected patients." (PMID 21299910, 2011). "Finally, mice lacking CXCR3 are more prone to liver fibrosis initiated by the loss of the anti-fibrogenic and angiostatic effects of CXCL9 on hepatic stellate cells and sinusoidal endothelial cells." (PMID 26731721, 2016). "Thus, CCR5, CXCR2, CXCR4 and CXCR6 antagonists or the application of CXCL9 may serve for prevention and treatment of liver fibrosis." (PMID 24646914, 2014). "In contrast to LyECs, Mcam, Fcgr2b (CD32b), Cxcl9, CD36, Kit, Clec4g, etc., genes were highly expressed in LSECs from CCl4-induced liver fibrosis, NASH and BDL mice." (PMID 36632228, 2023). "For instance, the overexpression of CCR1, CCR5, and CXCL4 can contribute to progression of liver fibrosis, whereas the stimulation of CXCR3 and CXCL9 exert the protective function of liver fibrosis." (PMID 35656309, 2022). "CXCL9, CXCL10, and CXCL 16 attract lymphocytes or natural killer (NK) cells involved in hepatic inflammatory pathogenesis and accelerate hepatic fibrosis progression." (PMID 33603714, 2020). "In a recent article published by our group, we found that CXCL9 rs10336 AA, CXCL10 rs3921 CC and CXCL11 rs4619915 AA genotypes were related to higher likelihood of severity of liver fibrosis in HIV/HCV-coinfected patients under a recessive model." (PMID 28755163, 2017). "In addition, we demonstrated that CXCL9 and CXCL10 suppressed the fibrosis associated gene expression in liver non-parenchymal cells and primary HSCs of mice in schistosomiasis and TGF-β -activated human hepatic stellate cells LX-2, suggesting their potential anti-fibrosis role in liver fibrosis." (PMID 22905138, 2012). "On the other hand, CXCL9 and IFIT3 were reported to relate to liver fibrosis in chronic hepatitis C patients." (PMID 21886832, 2011). "Within patients with CHD, CXCL9–11 mRNA expression did not correlate significantly with histological activity (Metavir) or liver fibrosis (Ishak) using Spearman correlation." (PMID 39980752, 2025). "Serum CXCL9 levels are much higher in patients with than without NASH, which suggests CXCL9/CXCR3 signaling as a target for the treatment of liver fibrosis." (PMID 28420094, 2017). "The CXCR3 ligands CXCL4, CXCL9 and CXCL10 seem to have divergent functions in liver fibrosis." (PMID 24646914, 2014). "Marked induction was observed in the anti-fibrotic chemokines such as CXCL9, suggesting that IFN treatment might lead not only to HCV eradication but also prevention and repair of liver fibrosis." (PMID 21886832, 2011). "Meanwhile, expression of α-SMA was inhibited in LX-2 by CXCL9 but not CXCL10, suggesting the different function of CXCR3 associated chemokines in liver fibrosis and that the various chemokines might affect HSCs via non-chemokines receptors as other researchers reported." (PMID 22905138, 2012).
pancreatic cancer (24 papers, 2017 to 2025). "Moreover, Sin3A loss leads to decreased expression of Cxcl9, Ifng, and Tnfa in pancreatic tumor tissues, suggesting that SIN3A plays a distinct role in the regulation of the TIME, differing from that of SIN3B." (PMID 39316363, 2024). "We found an association of increased expression of CXCL9, CXCL10, and CXCL10 with decreased survival in pancreatic cancer and CXCL5 in cholangiocarcinoma." (PMID 35740353, 2022). "CCL4, CCL5, CXCL9, and CXCL10 are associated with CD8+ T cells in pancreatic cancer." (PMID 38887558, 2024). "Together, our results support that Cxcr3, potentially by interacting with Cxcl9/Cxc10 + cDC1s in the spleen, promotes GzmB + cytotoxic T cells that may mitigate pancreatic cancer metastasis." (PMID 36472588, 2023). "The role of CXCL10 in pancreatic cancers seems clear, while that of CXCL9 remains undefined." (PMID 31913856, 2020). "Moreover, it is possible that PD-L1 activities are connected to chemokine-related pathways also in other aspects, as evidenced by the association of PD-L1 with the chemokine CXCL9 in basal patients and by the cooperativity between CXCR4 (CXCL12 receptor) and PD-L1 inhibitors in pancreatic cancer." (PMID 35205789, 2022). "The data showed that most of chemokines, such as CX3CL1, CXCL16, CXCL3, CXCL9, and CXCL5, were significantly high expressed in pancreatic tumor tissues compared to normal tissues." (PMID 35478937, 2022). "The CXCR3 ligands CXCL9 and CXCL10 have been suggested to promote an anticancer immune response in several types of solid tumor, but their role in pancreatic cancer is still controversial." (PMID 35954489, 2022). "The CXC ligand family (CXCL5, CXCL9, CXCL10, CXCL11, and CXCL17) plays a vital role in regulating pancreatic cancer progression." (PMID 33393862, 2021). "CXCL9, CXCL10 and CXCL11 have been previously shown to be effective in supporting an adequate antitumoral response in various cancers, although results in pancreatic cancer have been conflicting." (PMID 39885986, 2024). "Previous reports showed that CXCL9, CXCL10, and CCL5 could mark T cell–inflamed phenotype of pancreatic cancer." (PMID 35692828, 2022). "The direct or indirect effects of IL-6, IL-8, IL-10, TGF-β, C-C motif chemokine ligand 2 (CCL2), C-X-C motif chemokine ligand 9 (CXCL9), and CXCL10, but not limited to those, on tumor immunity in patients with oral, breast, and pancreatic cancer have been investigated." (PMID 31281359, 2019). "Our data also suggest that the ligands for the chemokine receptors CXCR3 (CXCL9, CXCL10, CXCL11) and CCR5 (CCL8) might affect the spatial distribution of CD8+ T cells in human pancreatic tumor tissues and enhance the relative T cell trafficking into tumor rich areas." (PMID 35954489, 2022). "Notably, the T cell chemokine attractants CCL5, CXCL9 and CXCL10 were increased in DMXAA-treated tumors, macrophages and DCs, as well as KPC1242 epithelial tumor cells, suggesting that these chemokines could participate in the recruitment of T cells to STING agonist-treated pancreatic tumors." (PMID 31036082, 2019).
diabetes (19 papers, 2013 to 2025). "Our findings reveal a positive correlation between CXCL9 levels and aging, underscoring the necessity of further research to clarify its role in diabetes and its broader implications in ARDs and mortality risk stratification." (PMID 40629349, 2025). "Additionally, single-cell RNA sequencing analysis in the NOD model has identified a subset of pro-inflammatory macrophages (Cxcl9 expressing macrophages), that are highly pathogenic in diabetes initiation." (PMID 41000615, 2025). "In individuals with diabetes, circulating C-X-C motif ligands (CXCL9 and CXCL10) levels are significantly elevated, which have been associated with the recruitment of T helper cells 1 and 17 into the kidney." (PMID 38542060, 2024). "CXCL9 is expressed in pancreatic β cells in response to pro-inflammatory cytokines, and deletion of the gene encoding its receptor CXCR3 accelerates diabetes in the NOD mouse." (PMID 37164005, 2023). "Higher levels of the Th1‐associated chemokine CXCL9 were detected in patients with T1D and DPN after two to three decades of diabetes duration compared to healthy control subjects." (PMID 37021432, 2023). "MSCs significantly reduced T cell (45%) and CXCL9-positive macrophage (67%) accumulation in the islets and the occurrence of diabetes." (PMID 35511238, 2022). "The CXCL9-positive macrophages were also observed in the islets of a cancer patient who developed diabetes following the administration of ICIs but few CXCL9-positive macrophages were observed in a control patient." (PMID 35511238, 2022). "A pronociceptive role for CXCL9 within the dorsal horn would provide further support for the use of chemokine antagonists in the treatment of diabetic neuropathic pain." (PMID 25789329, 2015). "The changes observed in our study in the mRNA and protein levels of CXCL9 during diabetic neuropathy suggest its very important role in the neuropathic pain that develops in diabetes." (PMID 25789329, 2015). "In men, adding CXCL9 as a continuous variable to a model, which already contained age at blood draw, dialect group, BMI, smoking, and history of diabetes, further increased the AUC (95% CI) from 0.65 (0.55, 0.76) in Model 2 to 0.74 (0.65, 0.83) in Model 3 for the prediction of hip fracture." (PMID 35810382, 2022). "Similarly, other authors described an increase in CXCL9 expression in the spinal cord and serum level of animal models of streptozotocin-induced diabetes, an autoimmune encephalomyelitis model, and locally inflamed DRG." (PMID 34681732, 2021). "T cells, macrophages and monocyte-derived macrophages expressing C-X-C motif chemokine ligand 9 (CXCL9) in pancreatic sections of NOD mice and a cancer patient who developed diabetes following the ICI treatments were analysed by immunofluorescence." (PMID 35511238, 2022). "To date, limited studies have investigated circulating CXCL9 levels in individuals with diabetes, and none have explored its prognostic value for mortality." (PMID 40629349, 2025). "Previous work has proposed CXCL-9 and CXCL-10 as potential biomarkers of type 1 diabetes mellitus." (PMID 38742118, 2024). "Although T cells were reported to accumulate in the islets of human patients, CXCL9-positive macrophages have not been tested in the pancreas specimens of human patients who developed diabetes after receiving ICIs." (PMID 35511238, 2022). "In conclusion, the results of our study suggest that increased spinal levels of CXCL1, CXCL5, CXCL9, or CXCL12 protein in mice after STZ treatment may participate in the development of diabetic neuropathic pain." (PMID 25789329, 2015).
hepatocellular carcinoma (18 papers, 2010 to 2026). A malignant tumor that arises from hepatocytes. "In mouse models, a chronically increasing trend in CXCL9 levels was associated with the progression from NAFLD to hepatocellular carcinoma in male mice." (PMID 35514751, 2022). "Multivariate analysis showed that CK19 (P= 0.043) and CXCL9 expression (P= 0.015) were independent risk factors in predicting the prognosis of hepatocellular carcinoma patients." (PMID 33854600, 2021). "We newly found that proinflammatory IL-17+ cells in the peritumoral stroma stimulated hepatoma cells to produce CXCL9, CXCL10 and CXCL11, which in turn led to CXCR3+ B-cell recruitment, maturation and IgG production." (PMID 27853178, 2016). "However, in hepatocellular carcinoma studies, CXCL9 binds to the receptor subtype CXCR3 and activates the rhCXCL9-induced p-ERK1/2-MMP2/MMP9 pathway, enhancing the migration and invasion of CD133+ hepatocellular carcinoma." (PMID 36479091, 2022). "In a separate hepatocellular carcinoma cohort, we replaced the stromal component with specific immune cell types—CXCR3+CD68+ or CD8+—to profile their spatial relationships with CXCL9+CD68+ cells." (PMID 39965007, 2025). "High CXCL9 and CXCL10 levels inhibit cytolytic CD8+ T cell expression of CXCR3 in hepatocellular carcinomas, and this, in turn, limits lymphocyte recruitment and tumor defense." (PMID 26462153, 2015). "Similar roles for CXCL9, CXCL13 and CXCL16 in T- and B-cell recruitment have been suggested in other models of liver disease including chronic Hepatitis C, Hepatocellular Carcinoma, Primary Biliary Cirrhosis and Primary Sclerosing Choliangitis." (PMID 20161726, 2010).
myocarditis (18 papers, 2010 to 2025). Myocarditis is a condition that is characterized by inflammation of the heart muscle (myocardium). "Moreover, a single nucleotide polymorphism in the CXCL9 gene, associated with a reduced risk of developing severe CCC in a cohort study, was associated with reduced CXCL9 expression and intensity of myocarditis in CCC." (PMID 24330528, 2013). "However, only the CXCL9 rs10336 GG polymorphism was associated with reduced intensity of myocarditis; significantly, only myocardial mRNA levels of CXCL9 were strongly associated with intensity of myocarditis." (PMID 25210230, 2014). "Increased mRNA levels of Th1 T-cell markers CCR5 and CXCR3, as well as their chemokine ligands, are found in CCC heart tissue; mRNA levels of Th1 T cell–chemoattracting chemokine CXCL9 in CCC hearts were positively correlated with the intensity of myocarditis." (PMID 40297326, 2025). "As for myocarditis, the expansion of CXCL9/10+CCR2+ macrophages and CXCR3hi CD8+ T lymphocytes is linked to the pathogenesis of ICI‐associated myocarditis, highlighting the therapeutic potential of CXCR3 pathway modulation." (PMID 40787068, 2025). "CCL5 and CXCL9 were the most highly expressed chemokine mRNAs, and the intensity of the myocardial inflammation was positively correlated with CXCL9 mRNA expression." (PMID 30559742, 2018). "Locally produced chemokines such as CCL2, CCL5, and CXCL9 play a major role in inflammatory cell recruitment to the heart in T. cruzi-induced acute myocarditis in mice as well as chronic human Chagas disease myocarditis." (PMID 25210230, 2014). "CXCL9 mRNA expression directly correlated with the intensity of myocarditis, as well as with mRNA expression of CXCR3, CCR4, CCR5, CCR7, CCR8 and their ligands." (PMID 23150742, 2012). "We found a positive correlation between mRNA expression of CXCL9 and the histopathologically assessed intensity of myocarditis." (PMID 23150742, 2012). "Significantly, the same CXCL9 (rs10336) genotype was also associated with cardiac expression of CXCL9 mRNA and intensity of myocarditis in the hearts of CCC patients, indicating this is a functional variant that regulates gene expression and myocarditis intensity." (PMID 40297326, 2025). "Moreover, it has been shown that elevated CXCL9 mRNA expression level is directly proportional to the severity of myocarditis." (PMID 35794867, 2022). "While it has been shown that CXCL10 is higher in patients with CCC, and polymorphisms in CXCL9 and CXCL10 are responsible for their altered expression patterns, CXCR3 expression on CD8+ cells is inversely proportional to the intensity of myocarditis." (PMID 35794867, 2022). "Together with the finding of a correlation between expression of CXCL9 and intensity of myocarditis, these results suggest that CXCL9 may be a master regulator of chemokine-driven inflammatory cell migration to CCC heart tissue." (PMID 23150742, 2012). "Since TNF-α and IFN-γ can increase endothelial CXCL9 expression, increased TNF-α and IFN-γ mRNA expression may have induced CXCL9 expression and facilitated myocarditis in the macaques that received CART." (PMID 21203448, 2010). "Interferon-responsive CXCL9+/CXCL10+ macrophages have emerged as a conserved pro-inflammatory myeloid subset in diverse cardiac injuries, including immune checkpoint inhibitor myocarditis and viral myocarditis." (PMID 41412038, 2025). "Results may indicate that genotypes associated to reduced risk in closely linked CXCL9 and CXCL10 genes may modulate local expression of the chemokines themselves, and simultaneously affect myocardial expression of other key chemokines as well as intensity of myocarditis." (PMID 23150742, 2012). "CXCL9/10+ macrophages and CXCR3hi CD8+ T cells were also found in biopsies from human hearts affected by ICI-myocarditis, suggesting their interaction as a potential novel target for pharmaceutical treatment of ICI-myocarditis." (PMID 39039301, 2025).
myocarditis (continued). "Similarly, the expansion of CCR2+ CXCL9/10+ macrophages, along with CXCR3hi CD8+ T cells, was seen in a preclinical model of myocarditis in MRL/Pdcd1−/− mice." (PMID 39023770, 2025). "Most tested patients (six of seven patients) had serum increases in the inflammatory cytokine interleukin (IL)-6 and in the chemokines CXCL9, CXCL10, and CXCL13, and the mass cytometry phenotypes of immune cell populations in the blood also showed correlations with myocardial inflammation." (PMID 34686542, 2021).
Sepsis (16 papers, 2014 to 2025). Sepsis is defined as life-threatening organ dysfunction caused by a dysregulated host response to infection. "Both, excessive pro-inflammatory responses with high IFNγ and downstream mediators, such as chemokines (CXCL9), as well as immunosuppression with low IFNγ levels are associated with unfavorable outcomes in sepsis." (PMID 40762872, 2025). "SAA3, CXCL9, and Orm1 are induced by pulmonary inflammation, while Pon1 is associated with oxidative stress in sepsis caused by MRSA (40, –, 43)." (PMID 38323827, 2024). "The top ten differentially expressed genes in this study include Gm29879, Lcn2, Cxcl10, Zbp1, Lbhd2, C5aR1, Cxcl10, Lbhd2, Cxcl9, and Fpr1, all of which might play a role in the pathophysiology of sepsis-induced WMI." (PMID 41584453, 2025). "Importantly, as visualized by intravital 2-photon microscopy, exogenous administration of CXCL9/10 was sufficient to correct sepsis-induced impairments in recruitment of effector cells at the localized site of TRM antigen recognition." (PMID 28910403, 2017). "However, sepsis prevented efficient recruitment of CTV+ cells upon TRM peptide activation that was restored after exogenous CXCL9/10 administration suggesting a potential way to correct sepsis-induced impairments in effector cell recruitment to the site of localized infection/inflammation." (PMID 28910403, 2017). "Published data demonstrate that interferon-γ–inducible chemokines, particularly CXCL9, are significantly higher in HLH compared with sepsis, whereas IL-6 is elevated in both conditions but typically reaches higher levels in sepsis." (PMID 41234904, 2025). "In agreement, another study reported an inverse relationship between the plasma levels of IL-6, MMP-8 and CXCL9 (indicative of systemic inflammation) and the TNF production capacity of whole blood obtained from patients with sepsis." (PMID 37415223, 2023). "For the chemokines, CCL2 and CCL3 levels were elevated in the middle sepsis phase (12 h), while CCL5, CXCL9, and CXCL10 levels were significantly increased in the late phase." (PMID 31354717, 2019). "We determined IFN-γ produced shortly after sepsis induction altered IFN-γR1 expression and function of vascular endothelium leading to impairments in VCAM-1 and CXCL9 expression upon exposure to exogenous or TRM-derived IFN-γ." (PMID 28910403, 2017). "CXCL9 is an interferon (IFN)-γ-induced chemokine, the levels of which correlate with the IFN-γ activity in HLH, and it has been shown to aid differentiation between HLH and sepsis in pediatric patients." (PMID 37629407, 2023). "Thus, targeting the chemokine axes CXCL9, CXCL10, which are involved in T and NK cell mobilisation, might be helpful to treat COVID19 as previously found in experimental sepsis." (PMID 34987646, 2022). "First, biomarkers of T-cell activation and IFNγ-activity (e.g. GZMB, PDL1, LAG3, CXCL9) were present broadly in IHF, including hyperferritinemic sepsis, and were not unique to one diagnosis (PC1)." (PMID 39264477, 2024). "The negative interactions for the sepsis group were between CCL5 and CXCL9, CCL5 and IL-5, and IL2R and IL-17A." (PMID 35811678, 2022). "Downstream induction of CXCL9 (but not of CXCL10 and 11) occurring in a subset of patients with high IFNγ levels has been shown to correlate with the hyper-inflammatory phenotype of sepsis." (PMID 40762872, 2025).